SHBG (sex hormone binding globulin)
Diseases named in the same sentence as SHBG in open-access papers (continued):
Sharing a sentence is not in itself a finding about the gene and the disease.
Insulin resistance (continued). "Insulin resistance causes inflammation in the body, lowers sex hormone binding globulin (SHBG) levels in obese men, may affect the secretion of male sex hormones, and further exacerbates obesity, which is known to have a negative impact on the quality of semen." (PMID 36613051, 2022). "Hyperinsulinemia caused by insulin resistance acts on gonadotropins together with luteinizing hormone (LH) increases androgen production in follicular membrane cells and reduces the production of sex hormone binding globulin in the liver, leading to the body's production of a hyperandrogen state." (PMID 34366917, 2021). "Along these lines, low serum SHBG level has been associated with increased adiposity and insulin resistance in children and adolescents; therefore, it has been hypothesized that SHBG might be an important regulator of puberty and a biomarker for cardiometabolic risk." (PMID 30925463, 2019). "However, it should be noted that interpreting the impact of decreased serum SHBG concentrations on NAFLD risk in women is limited by the fact that both factors known to be associated with decreased SHBG, androgen excess and insulin resistance, are highly prevalent in women with PCOS." (PMID 29590099, 2018). "In the present study, we examined the associations of estradiol, testosterone and SHBG with insulin resistance in premenopausal women, postmenopausal women and postmenopausal women who had received hormone therapy to clarify whether the associations differred depending on the estrogen status." (PMID 23825975, 2013). "The pooled sensitivity and specificity of SHBG levels for the assessment of insulin resistance were 74.7% and 66.9%, respectively." (PMID 41595721, 2026). "In the context of insulin resistance, elevated serum insulin levels increase ovarian androgen production and inhibit hepatic sex-hormone binding globulin (SHBG) production, thereby synergistically boosting free testosterone levels." (PMID 40529393, 2025). "It is known that greater blood insulin levels lead to insulin resistance, which in turn leads to weight gain, obesity and low SHBG concentrations." (PMID 40868462, 2025). "The review highlights that obesity disrupts hormonal balance, including reductions in sex hormone-binding globulin (SHBG) and testosterone levels, alongside increased insulin resistance and chronic inflammation." (PMID 40238039, 2025). "When compared to hs-CRP, which serves as a broad marker of systemic inflammation, SHBG provides more specific insights into androgen excess and insulin resistance." (PMID 40385768, 2025). "The analysis revealed that the genetically elevated mTOR gene level was associated with increased sex hormone-binding globulin (SHBG), a disorder implicated in obesity and insulin resistance." (PMID 40299431, 2025). "Specifically, insulin resistance reduces SHBG production, resulting in elevated bioavailable estrogen levels that promote mammary epithelial proliferation and tumorigenesis." (PMID 41036596, 2025). "Lower SHBG levels, often seen in obesity and insulin resistance, lead to higher bioavailability of estrogen, thereby promoting endometrial proliferation." (PMID 41427029, 2025). "Hyperinsulinemia and insulin resistance (IR) contribute to increased ovarian androgen production and a reduction in serum sex hormone-binding globulin (SHBG) levels, leading to higher circulating concentrations of free testosterone." (PMID 40428843, 2025). "Another marker of hepatic insulin resistance appears to be sex hormone-binding globulin (SHBG), which is produced mainly in the liver and synthesis of which is inhibited by hyperinsulinemia-compensating insulin resistance." (PMID 40430120, 2025). "Such a pattern reveals hepatic insulin resistance before the onset of dysglycaemia, positioning SHBG as a frontline biomarker for the early detection of stage-1 type-2 diabetes and hypoketonaemia-ICE." (PMID 41586225, 2025).
Insulin resistance (continued). "Recent studies have investigated the potential role of SHBG, a hepatic glycoprotein, in metabolic dysfunction, due to its inverse relationship with hyperinsulinaemia, insulin resistance and hepatic fat accumulation." (PMID 41586225, 2025). "Insulin resistance index was inversely and significantly correlatedwith sex hormone-binding globulin (r = -0.371; p < 0.001)." (PMID 40857627, 2025). "Experiments using adipose tissue cultures from obese horses with insulin resistance and controls revealed that adding SHBG restored levels of INSR, INRS1/2, Akt and Pi3k, implying improved insulin sensitivity, and tended to normalize the fatty acid profile." (PMID 40863113, 2025). "In the female population, decreased levels of SHBG were related to the development of insulin resistance (IR)." (PMID 40427034, 2025). "Insulin resistance leads to increased ovarian testosterone secretion, decreased secretion of sex hormone-binding globulin, and changes in adipokine levels, which disrupts the balance of the hypothalamic–pituitary-ovarian axis, leading to infertility." (PMID 40066003, 2025). "The significant relationship between the SHBG levels (nmol/L) and insulin resistance, i.e. the HOMA-R (mmol·μIU/ml), persisted in multiple regression analysis." (PMID 39014506, 2024). "SHBG is an FDA-approved biomarker, and its lower levels have been specifically linked to early-onset GDM and insulin resistance." (PMID 39589852, 2024). "SHBG, IGF-1, and Cortisol are all linked to glucose-lipid metabolism indices, and aberrant serum hormone expression is a major contributor to insulin resistance." (PMID 39876919, 2024). "The relationship between SHBG levels and insulin resistance was independent from total testosterone and from the free androgen index (FAI)." (PMID 39014506, 2024). "Patients with PCOS and low SHBG levels are prone to obesity, hyperandrogenism, insulin resistance, and infertility." (PMID 40255948, 2024). "Elevated SHBG levels were correlated with greater insulin resistance, suggesting a potential compensatory mechanism or a marker of underlying metabolic derangements." (PMID 39253627, 2024). "Insulin resistance and the consequent hyperinsulinemia can lead to increased serum testosterone levels and decreased SHBG levels, which in turn contribute to the increase of serum free testosterone, providing more substrate for peripheral estrogen conversion." (PMID 38909214, 2024). "On the other hand, obesity has been associated with decrements in testosterone levels, possibly as a result of aspects like alteration of the levels of SHBG and insulin resistance." (PMID 39840189, 2024). "The aim of the present study was to investigate in males on chronic hemodialysis the relationship of testosterone and SHBG serum levels with insulin resistance." (PMID 39014506, 2024). "Insulin resistance and hyperinsulinemia also increase androgen levels by promoting progesterone conversion to androgen in ovarian theca cells and decreasing SHBG levels in the liver, increasing free testosterone." (PMID 38589425, 2024). "A reduced serum SHBG level in PCOS patients serves as a significant risk factor for hyperandrogenemia and serves as a crucial predictor of insulin resistance, as well as disturbances in glucose and lipid metabolism." (PMID 38902677, 2024). "The incidence rates of hypertriglyceridemia, central obesity, and insulin resistance tended to decrease according to the elevated SHBG quartiles (all p for trend < 0.05)." (PMID 38988998, 2024). "Several studies demonstrated that SHBG levels were decreased in patients affected by insulin resistance and T2DM (type 2 diabetes mellitus)." (PMID 38892323, 2024). "The MAFLD group (N = 98) exhibited higher liver enzyme levels, more excellent insulin resistance, more pronounced obesity (both general and central), and lower SHBG levels compared to the healthy group (N = 74)." (PMID 39768643, 2024).
Insulin resistance (continued). "In previous studies, both insulin resistance status improvement and circulating insulin reduction have been shown to increase serum SHBG levels, thereby reducing the blood level of free testosterone in patients with PCOS." (PMID 39357046, 2024). "The metabolic PCOS subtype (37-39%) is characterized by a high BMI and insulin resistance with relatively normal LH and sex hormone binding globulin (SHBG) levels." (PMID 38734641, 2024). "By improving insulin resistance, they reduce hyperinsulinemia, decreasing ovarian androgen production and increasing levels of SHBG, which reduces free testosterone." (PMID 39599701, 2024). "Recent research has explored the potential role of sex hormone-binding globulin (SHBG) in metabolic disorders, given its association with insulin resistance (IR) and liver fat accumulation." (PMID 39768643, 2024). "Our findings on sex differences for SHBG, glucose homeostasis and T2D are in line with previous studies, showing in general higher SHBG levels, lower glucose levels, lower insulin resistance and lower incidence of T2D in women compared to men." (PMID 38954350, 2024). "Studies indicate that insulin exerts a regulatory influence on SHBG biosynthesis, showing an inverse relationship with insulin resistance." (PMID 39876919, 2024). "An animal study showed that pioglitazone significantly elevated serum and hepatic SHBG levels, considerably improving triglyceride and total cholesterol levels, insulin resistance, and hyperandrogenemia in rats with polycystic ovary syndrome." (PMID 38751428, 2024). "In the multiple regression-analysis independent predictors of insulin resistance were both SHBG levels and BMI." (PMID 39014506, 2024). "Obesity is associated with increased visceral adipose tissue, which results in elevated androgen production, decreased sex hormone binding globulin, elevated hyperinsulinemia, and insulin resistance in females." (PMID 38463925, 2024). "Hyperinsulinemia or insulin resistance can directly or indirectly stimulate the activity of osteoblast cells by suppressing the production of two binding proteins (sex hormone-binding globulin and insulin-like growth factor-binding protein)." (PMID 38111425, 2023). "Hyperinsulinemia from insulin resistance contributes to hyperandrogenism via stimulation of ovarian androgen secretion and inhibition of hepatic sex hormone-binding globulin synthesis, leading to follicle arrest and anovulation." (PMID 37727373, 2023). "Previous researches have shown that low serum SHBG is related to obesity, insulin resistance, compensatory hyperinsulinemia, and is a biomarker for abnormal glucose and lipid metabolism, type 2 diabetes, and cardiovascular diseases." (PMID 37308949, 2023). "Both liver steatosis and insulin resistance result in decreased sex hormone-binding globulin (SHBG) synthesis." (PMID 37559928, 2023). "Waist-to-hip ratio, sex-hormone binding globulin, insulin resistance, and gestation weight gain before 24 weeks were significantly associated with GDM in Chinese women with PCOS." (PMID 38234933, 2023). "The study aimed to estimate the cut-off value for homeostatic model assessment for insulin resistance (HOMA-IR) discriminating the insulin resistance based on the sex hormones binding globulin (SHBG) level in women with polycystic ovary syndrome (PCOS)." (PMID 36968815, 2023). "According to this meta-analysis, women with PCOS with low levels of SHBG were more likely to suffer from hyperandrogenism, insulin resistance, carbohydrate intolerance, type 2 diabetes, obesity, and cardiovascular disease." (PMID 37568345, 2023). "Specifically, these women exhibit an increased free androgen index (FAI), higher insulin resistance, elevated fasting blood glucose levels, lower levels of sex hormone-binding globulin (SHBG), higher levels of testosterone (T), and more prominent hirsutism." (PMID 37432488, 2023).
Insulin resistance (continued). "Serum levels of SHBG measured in this study were 31% lower in the group of men with insulin resistance." (PMID 37763034, 2023). "The present study reveals that the use of GLP-1RAs contributes to a higher natural pregnancy rate and a more regular menstrual frequency, improvement in obesity, insulin resistance, gonadal parameters mainly on SHBG." (PMID 37940910, 2023). "It is consistent with the results of a previous study analyzing the correlation between SHBG levels and insulin resistance in postmenopausal women." (PMID 36968815, 2023). "In insulin resistance, higher insulin levels leads to reduced synthesis and secretion of sex hormone binding globulin (SHBG) levels by the liver." (PMID 37836508, 2023). "HOMA-IR calculation is highly variable; therefore, requiring a wider analysis of insulin resistance based on various indicators, perhaps including SHBG." (PMID 36968815, 2023). "According to our analysis, inositols increase the concentration of SHBG, mainly due to their effect on insulin resistance." (PMID 36703143, 2023). "SHBG is a well-known marker of insulin resistance in diabetics and low levels have been reported in adolescent girls (known to be at risk for PCOS and insulin resistance)." (PMID 36829146, 2023). "In our study, the empirically estimated HOMA-IR cut-off point discriminating the insulin resistance based on the SHBG level below the lower limit of the laboratory reference range (< 26.1 nmol/L) was 2.1." (PMID 36968815, 2023). "It has also been shown that SHBG levels were inversely proportional to the severity of fatty liver, insulin levels and homeostatic model assessment for insulin resistance (HOMA-IR) values." (PMID 36968815, 2023). "These factors include sex-hormone binding globulin levels, cholesterol, triglycerides, and the degree of peripheral insulin resistance." (PMID 37546111, 2023). "A low serum level of SHBG is considered a marker of insulin resistance (inhibition of hepatic synthesis of SHBG due to compensatory hyperinsulinism)." (PMID 37568345, 2023). "Insulin resistance and hyperinsulinemia can increase androgen secretion and reduce the level of sex hormone-binding globulin (SHBG), thus leading to hyperandrogenemia, weight increase and obesity." (PMID 37608312, 2023). "A reduction in the SHBG concentration, a globulin produced mainly in the liver, is associated with PCOS and is a marker of the severity of hepatic insulin resistance." (PMID 37763034, 2023). "These finds deliver new insights in using SHBG protein as a novel therapeutic target for metabolic syndrome and insulin resistance intervention." (PMID 37697311, 2023). "SHBG is an important surrogate marker of insulin resistance, which mediates the hyperandrogenism in PCOS." (PMID 37015099, 2023). "Insulin resistance is often accompanied by nutrient oversupply and high dietary intake of monosaccharides can induce low serum SHBG levels through increasing hepatic lipogenesis." (PMID 37405618, 2023). "There are some confounders that should be considered when analyzing HOMA-IR values and corresponding cut-off points discriminating the insulin resistance based on the SHBG level." (PMID 36968815, 2023). "This phenomenon affects insulin resistance by lowering the sex hormone binding globulin concentration of the blood and changing the body fat distribution from gynoid to android type." (PMID 37095574, 2023). "Equine metabolic syndrome strongly impairs the endocrine properties of subcutaneous adipose tissue by altering lipid metabolism homeostasis and promoting low-grade inflammation, which collectively trigger insulin resistance in relation to depleted SHBG levels." (PMID 38146533, 2023). "It has been shown that lower SHBG levels are associated with lower G/I ratios and higher HOMA indices (consistent with insulin resistance) in women with PCOS." (PMID 36829146, 2023).
Insulin resistance (continued). "These correlations indicate that hyperinsulinemia and insulin resistance explain nearly 50% variability of SHBG concentrations." (PMID 36968815, 2023). "Recently, the correlation between serum sex hormone binding globulin (SHBG), inflammation, and insulin resistance has been demonstrated in obese and MetS human patients." (PMID 38146533, 2023). "In pregnant Chinese women with PCOS, pre-pregnancy waist-to-hip ratio, SHBG, insulin resistance, and gestation weight gain before 24 weeks were found to be strong risk factors and predictors of GDM development." (PMID 38234933, 2023). "Insulin resistance and hyperandrogenism, particularly in the context of sex hormone-binding globulin suppression, play a central role in PCOS pathogenesis." (PMID 38288169, 2023). "Obese children tend to develop an early onset of puberty and have increased insulin production, which promotes the release of gonadotropins and decreases the level of sex hormone-binding globulin, contributing to insulin resistance." (PMID 37964223, 2023). "A prevailing theory suggests that insulin resistance exacerbates hyperandrogenism by influencing the synthesis of sex hormone-binding globulin and increasing androgen production from adrenal and ovarian sources." (PMID 38288169, 2023). "Sex hormone binding globulin (SHBG) deteriorated expression has been recently strongly correlated to increased level of circulating pro-inflammatory cytokines and insulin resistance, which are typical manifestations of equine metabolic syndrome (EMS)." (PMID 37402098, 2023). "As SHBG levels are also effected by factors related to metabolism, such as insulin resistance and lipid profiles, which can be influenced by both lead exposure and BMI." (PMID 37534216, 2023). "Dietary modification has been shown to reduce insulin resistance and increase serum sex hormone-binding globulin levels compared with metformin." (PMID 37374308, 2023). "Insulin resistance increases inflammation, lowers male sex hormone release, lowers sex hormone binding globulin levels, and aggravates obesity." (PMID 38203349, 2023). "In conclusion, this is the first study estimating the probability of liver insulin resistance and impaired fasting glucose occurrence based on SHBG levels in women with PCOS." (PMID 35140785, 2022). "It addition, the percentage of women with insulin resistance and with SHBG level below the lower limit of the reference range (<26.1 nmol/L) was the highest in the subgroup with obesity and the lowest in the normal weight subgroup." (PMID 35140785, 2022). "In turn, insulin resistance, decreasing hepatic sex hormone-binding globulin production, increases free androgen levels, leading to follicular miniaturization and alopecia." (PMID 34897595, 2022). "Insulin and insulin resistance suppresses SHBG production, resulting in increased circulating free testosterone levels and enhanced hyperandrogenism." (PMID 36457554, 2022). "Second, excess of androgens and lower levels of SHBG have a direct effect on insulin resistance and T2D." (PMID 36505380, 2022). "While insulin resistance decreases hepatic sex hormone-binding globulin production and increases the availability of free testosterone, it thereby renders free testosterone a substrate for excessive aromatization to estradiol in adipose tissues." (PMID 36686453, 2022). "More than that, low circulating levels of testosterone and sex-hormone-binding globulin (SHBG) were reported to be associated with increased cardiovascular risk in men, possibly due to effects on insulin resistance and glycemia." (PMID 35382807, 2022). "Women with obesity are more likely to develop insulin resistance, which reduces the concentration of sex hormone-binding globulin in the body, resulting in an increase in bioavailability of estrogen." (PMID 36387921, 2022).